ALG13 (ALG13 UDP-N-acetylglucosaminyltransferase subunit)
Description:
Catalytic subunit of the UDP-N-acetylglucosamine transferase complex that operates in the biosynthetic pathway of dolichol-linked oligosaccharides, the glycan precursors employed in protein asparagine (N)-glycosylation. The assembly of dolichol-linked oligosaccharides begins on the cytosolic side of the endoplasmic reticulum membrane and finishes in its lumen. The sequential addition of sugars to dolichol pyrophosphate produces dolichol-linked oligosaccharides containing fourteen sugars, including two GlcNAcs, nine mannoses and three glucoses. Once assembled, the oligosaccharide is transferred from the lipid to nascent proteins by oligosaccharyltransferases. On the cytoplasmic face of the endoplasmic reticulum, the dimeric ALG13/ALG14 complex catalyzes the second step of dolichol pyrophosphate biosynthesis, transferring a beta1,4-linked N-acetylglucosamine (GlcNAc) from UDP-GlcNAc to GlcNAc-pyrophosphatedolichol (Gn-PDol) to produce N,N'-diacetylchitobiosyl diphosphodolichol. N,N'-diacetylchitobiosyl diphosphodolichol is a substrate for ALG1, the following enzyme in the biosynthetic pathway. [Isoform 2]: Catalytic subunit of the UDP-N-acetylglucosamine transferase complex that operates in the biosynthetic pathway of dolichol-linked oligosaccharides, the glycan precursors employed in protein asparagine (N)-glycosylation. The assembly of dolichol-linked oligosaccharides begins on the cytosolic side of the endoplasmic reticulum membrane and finishes in its lumen. The sequential addition of sugars to dolichol pyrophosphate produces dolichol-linked oligosaccharides containing fourteen sugars, including two GlcNAcs, nine mannoses and three glucoses. Once assembled, the oligosaccharide is transferred from the lipid to nascent proteins by oligosaccharyltransferases. On the cytoplasmic face of the endoplasmic reticulum, the dimeric ALG13/ALG14 complex catalyzes the second step of dolichol pyrophosphate biosynthesis, transferring a beta1,4-linked N-acetylglucosamine (GlcNAc) from UDP-GlcNAc to GlcNAc-pyrophosphatedolichol (Gn-PDol) to produce N,N'-diacetylchitobiosyl diphosphodolichol. N,N'-diacetylchitobiosyl diphosphodolichol is a substrate for ALG1, the following enzyme in the biosynthetic pathway. [Isoform 1]: No glycosyltransferase or deubiquitinase activity is detected for this potential multifunctional enzyme.
Synonyms: CXorf45; GLT28D1; MDS031; YGL047W; FLJ23018; TDRD13; CDG1S; DEE36; EIEE36
Tractability: Antibody: UniProt places it where antibodies can reach, with high confidence. PROTAC: ubiquitination databases record sites on it; its protein half-life has been measured.
Gene: Protein-coding gene on chromosome X (111,665,811 to 111,760,649, forward strand). Ensembl gene ENSG00000101901.
Subcellular location: Endoplasmic reticulum membrane (Isoform 2)
Subcellular location (Human Protein Atlas): Vesicles; Cytosol
Pathways (Reactome):
Disease: Defective ALG14 causes ALG14-CMS
Metabolism of proteins: Biosynthesis of the N-glycan precursor (dolichol lipid-linked oligosaccharide, LLO) and transfer to a nascent protein
Gene Ontology:
Molecular function: N-acetylglucosaminyldiphosphodolichol N-acetylglucosaminyltransferase activity; protein binding; catalytic activity; hexosyltransferase activity
Biological process: dolichol-linked oligosaccharide biosynthetic process; protein N-linked glycosylation
Cellular component: cytoplasmic side of endoplasmic reticulum membrane; endoplasmic reticulum membrane; cytoplasm
Gene-disease validity (ClinGen):
ClinGen rates the evidence that ALG13 causes each of these diseases.
genetic developmental and epileptic encephalopathy (X-linked): Definitive. A complex neurodevelopmental disorder characterized by a range of developmental delays and epileptic encephalopathy phenotypes.
Homologues: Orthologues: chimpanzee ALG13 (99% identical), macaque ALG13 (98% identical), chimpanzee ALG13 (83% identical), guinea pig ALG13 (76% identical), pig ALG13 (71% identical), rat Alg13l1 (55% identical), mouse Alg13 (55% identical), tropical clawed frog alg13 (44% identical), zebrafish alg13 (33% identical), dog ALG13 (17% identical).
Diseases named in the same sentence as ALG13 in open-access papers:
ALG13 is named in the same sentence as 45 diseases in open-access papers, as found by Europe PMC text mining. Sharing a sentence is not in itself a finding about the gene and the disease. The quoted sentences say what the papers report.
epilepsy (13 papers, 2017 to 2026). A brain disorder characterized by episodes of abnormally increased neuronal discharge resulting in transient episodes of sensory or motor neurological dysfunction, or psychic dysfunction. "Deletion of the Alg13 gene has been identified as strongly associated with epilepsy susceptibility and seizure severity in mice." (PMID 41988489, 2026). "In conclusion, our findings demonstrate that mutations in ALG13 can led to epilepsy and alleviate GABAAR-mediated postsynaptic transmission." (PMID 33014431, 2020). "The reduced expression of the Alg13 gene signifies that the epilepsy-related neuropsychiatric pathology was attenuated via the regulation of GABA receptors in the IGF-1-injected APP/PS2 mice." (PMID 38473814, 2024). "Regarding epilepsy, most known ALG13-CDG patients have been treated with a combination of many antiepileptic drugs (AEDs), which unfortunately did not lead to adequate seizures control." (PMID 33807002, 2021). "ALG13-CDG clinical spectrum apart from epilepsy covers developmental delay (100%), intellectual disability (92%), hypotonia (85%), coagulation abnormalities and endocrine dysfunction." (PMID 33440761, 2021). "To further investigate the mechanism by which ALG13 affects the inhibitory postsynaptic current in epilepsy, we examined the effect of ALG13 on GABAAR regulation." (PMID 33014431, 2020). "However, the mechanisms of ALG13 by which deficiency leads to epilepsy are unknown." (PMID 33014431, 2020). "ALG13, ALG13 UDP-N-acetylglucosaminyltransferase subunit, is an enzyme involved in protein N-glycosylation, and is associated with an X-linked congenital glycosylation disorder with severe developmental delay, epilepsy and intellectual disability." (PMID 38982123, 2024). "Overall, these results reveal that ALG13 may be involved in the occurrence of epilepsy through the regulation of GABAAR function, and may provide new insight into epilepsy prevention and treatment." (PMID 33014431, 2020).
Epileptic encephalopathy (5 papers, 2018 to 2025). A condition in which epileptiform abnormalities are believed to contribute to the progressive disturbance in cerebral function. "ALG13 has been associated with several disease conditions including developmental and epileptic encephalopathy as well as genetic intellectual disability (Epi4K Consortium & Epilepsy Phenome/Genome Project, 2013;Bissar-Tadmouriet al., 2014;Nget al., 2020)." (PMID 37082000, 2023). "This manuscript describes the first metabolomic analysis using NMR in three patients with epileptic encephalopathy due to the recurrent c.320A>G variant in ALG13, characterized to date only in about 60 individuals (mostly female)." (PMID 33807002, 2021). "In our study, WES analysis enabled the diagnosis of ALG13-CDG in patients with early-onset drug-resistant epileptic encephalopathy." (PMID 33407696, 2021). "ALG13-CDG presents as an early infantile epileptic encephalopathy." (PMID 33807002, 2021). "Furthermore, the phenotype associated with mutations in ALG13 is one of epileptic encephalopathy not present in either the patient or the mother, who both carry the same sequence variation." (PMID 29441694, 2018).
Intellectual disability (5 papers, 2022 to 2026). "Through multiomic analysis, we have identified key pathways potentially contributing to seizures, intellectual disability, and developmental delays in ALG13-CDG, providing a mechanistic framework to inform future therapeutic development." (PMID 41597222, 2026). "Variants in the glycosyltransferase domain of ALG13, particularly c.320A>G, p.N107S, lead to ALG13-CDG, a severe disorder of glycosylation with predominantly neurological manifestations, including developmental delay, intellectual disability, seizures, and central hypotonia." (PMID 41597222, 2026). "The disruption of calcium signaling may, therefore, contribute to the complex neurological symptoms in ALG13-CDG, including seizures, developmental delays, and intellectual disability." (PMID 41597222, 2026).
developmental delay (4 papers, 2022 to 2026). "Specifically, the mutation in the gene ALG‐13 affects N‐linked glycosylation which can disrupt various metabolic pathways and often manifests as microcephaly, hepatomegaly, seizures, developmental delay, and generalized hypotonia." (PMID 39831135, 2025). "Altered glycosylation of integrins (ITA7, LG3BP) and the upregulation of PDPN may further destabilize these critical cell-ECM interactions, potentially explaining the developmental delays and seizure phenotypes observed in ALG13-CDG." (PMID 41597222, 2026). "Elevated lactosylceramide (Hex2Cer) levels, linked to oxidative stress and mitochondrial dysfunction, may contribute to the seizure and developmental delay phenotypes observed in ALG13-CDG." (PMID 41597222, 2026).
developmental and epileptic encephalopathy (3 papers, 2022 to 2026). An epilepsy associated with developmental impairment that may be due to either the underlying etiology or the superimposed epileptic activity, or both. "ALG13 variants underlie infantile-onset developmental and epileptic encephalopathy (DEE), while ALG14 gene mutants present as early lethal neurodegeneration with myasthenic and myopathic features, also known as congenital myasthenic syndrome (CMS)." (PMID 36200043, 2022). "Pathogenic variants in the asparagine‐linked glycosylation 13 homolog (ALG13) gene have been implicated in the aetiology of developmental and epileptic encephalopathy (DEE) 36 (OMIM:*300776, DEE36)." (PMID 39311797, 2024).
infantile spasms (3 papers, 2023 to 2025). A rare epilepsy syndrome characterized by onset of epileptic spasms in infants between 2 and 12 months of age, and rarely up to 24 months. "Missense variants in ALG13 are found mainly (but not only) in females with severe infantile spasms." (PMID 38328757, 2023).
microcephaly (3 papers, 2022 to 2026). A congenital or acquired developmental disorder in which the circumference of the head is smaller than normal for the person's age and sex. "Reduced levels of ECM-related proteins, such as RDH10 and RARA, linked to microcephaly, indicate that ECM dysregulation may contribute to the structural brain abnormalities reported in ALG13-CDG." (PMID 41597222, 2026).
developmental and epileptic encephalopathy, 36 (2 papers, 2021 to 2024). "We report on a male with developmental and epileptic encephalopathy 36 (DEE36) with ID, the third reported male in the literature to date with the most common pathogenic variant in ALG13: c.320A>G; p.(Asn107Ser)." (PMID 39311797, 2024). "ALG13-CDG, known as an early infantile epileptic encephalopathy-36 (EIEE36), is caused by heterozygous mutation in the ALG13 gene, located on chromosome Xq23." (PMID 33440761, 2021).
neuroblastoma (2 papers, 2019 to 2023). Neuroblastoma (NB) is the most common solid, extracranial childhood tumor. "Interestingly, ALG13 (an early target of miR-34a) was reported as correlated with worse clinical outcomes for neuroblastoma." (PMID 31349573, 2019). "hsa-miR-34a has been reported to regulate ALG13, FUT8, GALNT7, and ST3GAL5 in neuroblastoma and hepatocellular carcinoma." (PMID 37188790, 2023).
non-small cell lung carcinoma (2 papers, 2020 to 2023). A group of at least three distinct histological types of lung cancer, including non-small cell squamous cell carcinoma, adenocarcinoma, and large cell carcinoma. "High expression of ALG13 was associated with poor overall survival in non-small cell lung cancer." (PMID 33302383, 2020). "For example, high mRNA expression levels of OTUD1, OTUD3, OTUD4, and ALG13 are associated with improved prognosis in non-small cell lung cancer (NSCLC) and adenocarcinoma, but not in squamous cell carcinoma." (PMID 36829909, 2023).
ovarian tumor (2 papers, 2020 to 2022). "As the canonical human isoform, the longer ALG13-iso1 contains not only an N-terminal glycosyltransferase 28 domain, but also several other domains including an ovarian tumor deubiquitinase domain." (PMID 36200043, 2022). "It has been suggested that ALG13 ovarian tumor deubiquitinase domain may catalyze ubiquitination of certain protein targets, such as GTases in the LLO pathway." (PMID 36200043, 2022). "Besides containing the N-terminal GnTase catalytic domain, human ALG13-iso1 also contains an ovarian tumor deubiquitinase domain with predicted active sites in its C-terminal region." (PMID 36200043, 2022).
bladder cancer (1 paper, 2020). "Interestingly, DAPK3, the GMR of NOR, is part of the bladder cancer pathway, and ALG13, the GMR of CWM, is active in the N-glycan biosynthesis." (PMID 33302383, 2020).
breast carcinoma (1 paper, 2021). "Expression levels of ALG1, ALG2, ALG3, ALG8, ALG9, ALG12 and ALG13 were differentially upregulated in radioresistant breast cancer tissues compared with those in radiosensitive tissues, particularly ALG3 with the highest level (4.53-fold change)." (PMID 33931075, 2021).
congenital disorder of glycosylation (1 paper, 2024). Congenital disorder of glycosylation (CDG) is a fast growing group of inborn errors of metabolism characterized by defective activity of enzymes that participate in glycosylation (modification of proteins and other macromolecules by adding and processing of oligosaccharide side chains). "Deficiency of asparagine-linked glycosylation 13 (ALG13) causes a congenital disorder of glycosylation (CDG), usually with normal transferrin electrophoresis and consisting of a DEE." (PMID 38612920, 2024).
congenital disorder of glycosylation type I (1 paper, 2020). A congenital disorder of glycosylation involve disrupted synthesis of the lipid-linked oligosaccharide precursor. "Mutations of the ALG13 gene underlie congenital disorders of glycosylation type I (CDG-I), a rare human genetic disorder with defective glycosylation." (PMID 33014431, 2020).
eczema (1 paper, 2020). "Among non-PMM2-CDG, skin allergies—particularly eczema—were the most reported, especially in ALG13-, SRD5A3- and PIGA-CDG." (PMID 32635232, 2020).
glycosylation disorders (1 paper, 2021). "The presented NMR-based metabolomics results obtained for patients with ALG13-CDG caused by a c.320A>G variant provide an interesting preliminary insight into the laboratory characteristics of one of the glycosylation disorders." (PMID 33807002, 2021).
Hypsarrhythmia (1 paper, 2021). Hypsarrhythmia is abnormal interictal high amplitude waves and a background of irregular spikes. "There are also two male ALG13-CDG patients reports with refractory epilepsy with polymorphic seizures and another with c.320A>G variant in ALG13 with ESp and hypsarrhythmia on EEG, treated with VGB, prednisolone, valproic acid (VPA), nitrazepam (NZP), lamotrigine (LTG)." (PMID 33440761, 2021).
Lennox-Gastaut syndrome (1 paper, 2017). Lennox-Gastaut syndrome (LGS) belongs to the group of severe childhood epileptic encephalopathies. "The variant found in ALG13 (c.320A>G) in a patient with NLES who progressed to Lennox-Gastaut syndrome (LGS) has been previously reported (rs398122394) as pathogenic and is located in the region where glysosyltransferase activity resides." (PMID 29190809, 2017).
osteoporosis (1 paper, 2022). A condition of reduced bone mass, with decreased cortical thickness and a decrease in the number and size of the trabeculae of cancellous bone (but normal chemical composition), resulting in increased fracture incidence. "A study has identified ALG13 as a potential osteoporosis marker gene related to osteoclast activity and hypogonadal bone loss." (PMID 36575369, 2022).
Saul-Wilson syndrome (1 paper, 2023). "Additionally, de novo variants have been reported in CDG, mainly among ALG13-CDG females, Saul-Wilson syndrome and SLC35A2-CDG." (PMID 37858231, 2023).
Strabismus (1 paper, 2022). A misalignment of the eyes so that the visual axes deviate from bifoveal fixation. "However, other phenotypes, such as strabismus and absence of seizure in our second patient, are not reported if any, which may represent a unique case of X-linked recessive nonsyndromic disorder caused by a mutation in ALG13." (PMID 35899201, 2022).
metabolic disorder (3 papers, 2021 to 2025). "According to the bioinformatic analyses, the mutation itself is not deleterious; however, it causes a multisystemic metabolic disorder, called ALG13-CDG, in the patients with the c.320A>G mutation." (PMID 35327592, 2022).
neurological disorders (2 papers, 2017 to 2022). "In humans, mutations in ALG13 or ALG14 lead to severe neurological disorders with a multisystem phenotype, known as ALG13/14-CDG (congenital disorders of glycosylation)." (PMID 36200043, 2022). "Pathogenic mutations in human ALG13 or ALG14 cause severe neurological disorders with a multisystem phenotype." (PMID 36200043, 2022). "We identified four genes that had already been associated with neurological disorders (AFF2, ALG13, OPHN1, and RBM10)." (PMID 28769055, 2017).
tumor (2 papers, 2020). "However, most of our transcriptomic results (including tumor heterogeneity, activation of chemokine and VEGF signaling pathways, major roles of TASOR and ALG13) can explain functional and clinical observations of other authors." (PMID 33302383, 2020). "Additionally, the results of expression analysis on the data of Chinese Human Proteome Project (CNHPP) (110 paired tumor and nontumor tissues of clinical early‐stage HCC) showed consistently upregulation of protein level of OTUs (including OTUD7B, OTUD6B, ALG13, OTUB1, OTULIN) in HCC tissues." (PMID 32328410, 2020).
cancer (1 paper, 2020). A tumor composed of atypical neoplastic, often pleomorphic cells that invade other tissues. "We delineated the molecular mechanisms by which TASOR overexpression and ALG13 silencing would selectively affect the cancer cells with little consequences for the normal cells." (PMID 33302383, 2020). "Thus, silencing ALG13 would have both direct and indirect (mediated by CC genes) on the cancer cells." (PMID 33302383, 2020). "(ii) Owing to the death of the patient and the lack of FDA approval, we had no possibility to test the effects of TASOR and ALG13 expression manipulation on cancer nodules and normal tissue." (PMID 33302383, 2020).
neurodevelopmental disorder (1 paper, 2021). A behavioral and cognitive disorder with onset during the developmental period that involves impaired or aberrant development of intellectual, motor, or social functions. "In the case of CDG with the primary neurological phenotype (neurodevelopmental disorders), including ALG1-CDG, ALG3-CDG, ALG13-CDG, and DPAGT1-CDG, liver is affected in a minority of patients." (PMID 34291020, 2021).
ALG13 also shares sentences with these, for which no sentence is quoted: Angelman syndrome (1 paper); Anxiety (1); cervical cancer (1); channelopathy (1); coagulopathy (1); congenital heart disease (1); congenital myasthenic syndrome (1); cutis laxa (1); dilated cardiomyopathy (1); Dystonia (1); fructose intolerance (1); genetic disorder (1); infantile epileptic encephalopathy (1); Infertility (1); movement disorder (1); neuronal migration disorders (1); sensorineural hearing loss (1); uterine corpus endometrial carcinoma (1).